RBMY2FP (RNA binding motif protein Y-linked family 2 member F, pseudogene)
Synonyms: MGC26641
Gene: Transcribed unprocessed pseudogene on chromosome Y (22,310,864 to 22,321,825, forward strand). Ensembl gene ENSG00000243040.
Diseases named in the same sentence as RBMY2FP in open-access papers:
RBMY2FP is named in the same sentence as 1 disease in open-access papers, as found by Europe PMC text mining. Sharing a sentence is not in itself a finding about the gene and the disease.
RBMY2FP shares sentences with these, for which no sentence is quoted: Azoospermia (1 paper).